TCF7L2 (transcription factor 7 like 2)
Diseases named in the same sentence as TCF7L2 in open-access papers (continued):
Sharing a sentence is not in itself a finding about the gene and the disease.
tumor (continued). "Inducible silencing of either SOX9 or TCF7L2 potently increased apoptosis and decreased proliferation, resulting in suppression of tumor growth of the SOX9‐TCF7L2 double‐high GBC model in vivo." (PMID 39492805, 2024). "In conclusion, these findings indicated that the expression of SOX9 and TCF7L2 can delineate clinically meaningful tumor subgroups." (PMID 39492805, 2024). "This group was enriched in key WNT pathway TFs, such as LEF1, TCF7, and TCF7L2, which was corroborated by the chromatin accessibility landscape analysis of a cohort of tumor organoids established in this study." (PMID 39567475, 2024). "Tumours with SOX9 or TCF7L2 mutations had increased expression of the respective genes, while other mutant WNT pathway drivers had reduced tumour expression." (PMID 39112715, 2024). "With a different exogenous WNT-responsive reporter approach on the same CRC cell lines, TCF7 was identified as a positive regulator of CRC while TCF7L2 was shown to have tumor suppressor properties in CRC17." (PMID 38472198, 2024). "A tumour-specific upregulation of Lef1 and Tcf7 genes was observed, as well as downregulation of Tcf7l1, while Tcf7l2 expression was unaltered." (PMID 37907668, 2023). "We also detected COSMIC fusion VTI1A::TCF7L2 across multiple tumor and normal tissue types (consistent with Nome et al68)." (PMID 37323575, 2023). "Transplantation experiments in nude mice showed that elevated miR-22-3p repressed OS tumor growth and decreased TCF7L2, Wnt and β-catenin." (PMID 34753394, 2022). "IHC results indicated weaker tumor tissue expression of Ki67 in the sh-TCF7L2 group than in the sh-Ctrl group." (PMID 35864968, 2022). "The transcription factor 7-like 2 (TCF7L2) gene has been identified as a novel transcription factor involved in epithelial-mesenchymal transition (EMT) in tumor cells." (PMID 35654816, 2022). "Silencing TCF7L2 using miRNA in CCRCC lines causes cell sensitivity at a clinically relevant X‐ray dose, and the effect is restricted to tumor cells with high TCF7L2 activity." (PMID 34612510, 2022). "HNRNPA2B1 regulates Wnt signaling transcriptional activity by regulating the stability of TCF7L2 mRNA, and it is related to tumor growth." (PMID 36157216, 2022). "To clarify the functions of TCF7L2 in vivo, we established nude mouse models of subcutaneous tumor and lung metastasis by injecting MKN45 cells, according to previous reports." (PMID 35864968, 2022). "β-Catenin–mediated transcriptional activity is required for self-renewal frequency through interaction with the transcription factor TCF7L2 and disruption of this interaction reduces tumor volume of subcutaneous GSC xenografts." (PMID 33400685, 2021). "Cell adhesion-associated gene expression is correlated with TCF7L2 expression specifically in normal tissue, and with LEF1 and TCF7L1 in tumor tissue." (PMID 32403323, 2020). "Our meta-analysis confirms that among the four human LEF/TCF genes, LEF1 and TCF7 are preferentially expressed in tumor biopsies, while TCF7L2 and TCF7L1 in normal control tissue." (PMID 32403323, 2020). "TCF7L2 has been suggested to act as an oncogenic or tumor suppressor in colorectal and breast carcinomas." (PMID 32843642, 2020). "TCF7L2, Wnt1 and β‐catenin (nuclear) protein expression increased in tumours overexpressing SPRY4‐IT1." (PMID 31736268, 2020). "There is also evidence that Tcf7l2 is indispensable for tumor initiation which agrees well with the positive regulation of several oncogenes by TCF7L2." (PMID 32203164, 2020). "Silencing TCF7L2 expression inhibited tumour growth and significantly attenuated 18F-FDG uptake in this in vivo xenograft model." (PMID 29476053, 2018). "The TCF7L2 gene encodes TCF4, a tumor suppressor gene which cooperates with β-catenin in colorectal carcinogenesis." (PMID 29652830, 2018). "The results showed that high TCF7L2 expression was closely related to a low degree of tumour differentiation (P = 0.029) and to the status of lymph node metastasis (P = 0.042)." (PMID 29476053, 2018).
tumor (continued). "In a xenograft model of human skin SCC, we show that overexpression of TCF7L1 also promotes tumor growth while downregulation of TCF7L1 and its paralogue TCF7L2 decreases tumor growth." (PMID 28467300, 2017). "Consistent with the observation that silencing TCF7L1 and TCF7L2 reduced tumor size, their downregulation reduced SCC cell proliferation in vitro and in vivo." (PMID 28467300, 2017). "While the short summary above reflects the prevailing view, it should be noted that there are also reports supporting a role for TCF7L2 repressing Wnt signaling and acting as a tumor suppressor in a mouse model of CRC." (PMID 27527215, 2016). "TCF7L1 expression was upregulated in lines derived from metastatic tumours compared to primary tumours, while conversely both TCF7L2 and LEF1 were strongly downregulated in the metastatic lines." (PMID 27531891, 2016). "The potential tumor-genesis role of TCF7L2 suggested a novel method in tumor therapies, which is to inhibit TCF7L2 expression or to down-regulate its target genes’ expression." (PMID 26289446, 2015). "On the contrary, proliferation-promoted genes such as CTNNB1, CREB1, CREB5, and TCF7L2 were up-regulated 3.65-, 2.63-, 2.87-, and 5.75-fold respectively in tumor tissues." (PMID 23285163, 2012). "For example, tumor C3H BF had Wnt1 as a CIS in addition to Tcf7l2, while insertion of MMTV at Antxr1 and Wnt3 in tumor Balb 5 resulted in the expression of both CISs." (PMID 22087314, 2011). "In addition, MALAT1 promotes cell growth and tumor metastasis by controlling TCF7L2 expression via mTOR-mediated TCF7L2 translation, thereby facilitating aerobic glycolysis and repressing gluconeogenesis in HCC." (PMID 41361062, 2025). "In addition, to explore the function of TCF7L2 in somatotroph tumour, we performed vitro experiments and found that TCF7L2 positively regulates tumour cell proliferation and GH secretion." (PMID 38769659, 2024). "Our results revealed that TCF7L2 was upregulated in somatotroph tumours." (PMID 38769659, 2024). "This essential role positions TCF7L2 as a potential tumor promoter." (PMID 39435285, 2024). "Thus, we investigate the alternation in the genome architecture and gene expression of TCF7L2 and found that TADs gained and loops increased in the TCF7L2 gene area, with its expression being upregulated in the tumour." (PMID 38769659, 2024). "In addition, SK1 cells with stable TCF7L2 overexpression were injected into the tail veins of mice to construct lung metastasis models, and the tumor metastasis in the lung of mice was observed 8 weeks later." (PMID 39060928, 2024). "Of the members of this signaling pathway, the APC, AXIN1, TCF7L2, and RHOA genes are most frequently mutated, the latter encoding a low-molecular-mass protein that contributes to cell invasiveness, adhesion, migration, and polarization, and tumor metastasis." (PMID 37509254, 2023). "Additionally, we identified important transcriptional regulators for primitive tumor cells including TCF7L2/MEIS1-PAX6 and SOX transcriptional cascades." (PMID 36966348, 2023). "In our in vivo experiments, TCF7L2 promoted tumor growth and metastasis in nude mice." (PMID 35864968, 2022). "Furthermore, RT-PCR results showed that TCF7L2 expression in BC tumor samples was significantly upregulated compared to adjacent samples, and these results were confirmed by western blotting of four pairs of BC tissues." (PMID 35957803, 2022). "Finally, the influence of miR-22-3p/TCF7L2 axis on OS tumor growth was further examined in a xenograft assay in nude mice." (PMID 34753394, 2022). "Previous reports indicated that both FOSL1 and TCF7L2 had tumor suppressor activity." (PMID 34976185, 2022). "In vivo, we found that TCF7L2 promoted tumor growth and metastasis in nude mice." (PMID 35864968, 2022).
tumor (continued). "This new mechanism, which measures both chemo‐ and radio‐resistance, suggests that TCF7L2 could be a molecular target for sensitizing radiotherapy‐resistant tumor cells." (PMID 34612510, 2022). "Besides, the transcription factor 7-like 2 (TCF7L2) is correlated with the glycolysis in tumor cells." (PMID 32587480, 2020). "Its essential function in stimulating cell proliferation in the healthy murine intestine and its role in transmitting oncogenic Wnt/β-Catenin signals in mouse tumor models seemingly qualify TCF7L2 as a tumor-promoting factor also in human colorectal carcinogenesis." (PMID 32203164, 2020). "TCF7L2 is an important member in the Wnt signaling pathway and mutations in Wnt-related genes were also found to be enriched in MSI-H cases in a cohort of 67,000 pan-tumor cases." (PMID 32466784, 2020). "Since downregulation of both TCF7L1 and TCF7L2 in SCC cells were required to reduce xenografted tumor growth, it suggested that TCF7L1 and TCF7L2 can compensate for each other and that they may have a similar function in skin SCC." (PMID 28467300, 2017). "Additionally, we show that downregulation of TCF7L1 and its paralogue TCF7L2 reduces tumor growth in a xenograft model of human skin SCC." (PMID 28467300, 2017). "In a xenograft model of human skin SCC, downregulation of TCF7L1 and its paralogue TCF7L2 decreased tumor size, indicating that these two LEF/TCF family members, whose functions overlap in skin development, are required for the optimal growth of xenografted tumors." (PMID 28467300, 2017). "Importantly, overexpression of TCF7L2 also increased xenografted SCC tumor size, accelerated cell migration, and counteracted HRASG12V-induced senescence similarly as TCF7L1." (PMID 28467300, 2017). "In addition to the two positive control fusions involving TCF7L2, another TCF7L2 fusion with VWA2 as a novel upstream fusion partner was identified in one tumor sample." (PMID 26474385, 2015). "Since TCF7 could suppress TCF7L2, it might be a promising anti-tumor strategy to introduce TCF7 to tumor cells as a treatment." (PMID 26289446, 2015). "Although we did not identify a TCF7L2-VTI1A translocation, we did detect a TCF7L2 mutation in one tumor." (PMID 24943349, 2014). "The tumor suppressor gene and epithelial cell marker E-cadherin (Cdh1) was markedly up-regulated and the oncogenic transcription factor Myc was down-regulated by Tcf7l2 silencing." (PMID 25414334, 2014). "Additionally, we discovered that the increased m6A modification levels in tumor cell TCF7L2 were primarily enriched in the 3′-UTR, which aligns with the prevailing notion that most m6A residues exhibit 3′-UTR localization bias and are associated with mRNA instability." (PMID 38390305, 2024). "On the other hand, TCF7L2 manifests an anti-tumor function by suppressing cell motility and invasiveness and by directly suppressing the activity of the pro-metastatic RUNX2–Runt-related transcription factor 2, its loss of function stimulating tumor malignancy." (PMID 37509254, 2023). "However, the loss of TCF7L2 promotes migration and the invasion of human CRC by suppressing the expression of pro-oncogenic transcription factor RUNX2 and cell adhesion molecules, supporting tumour-suppressive functions." (PMID 35860598, 2021). "As a caveat, the available genomic data and information about variant allele frequencies do not reveal whether a given tumor sample harbors one or two defective TCF7L2 alleles." (PMID 32203164, 2020).
tumor (continued). "Likewise, a heterozygous G→T transition within TCF7L2 leading to a glutamine to lysine substitution at codon 51 was observed in both the parental tumor and the first- and second-generation xenografts with the mutant and wild type transcripts maintained at a consistent ratio." (PMID 24278200, 2013). "Also, Tcf7l2 appeared to be induced in tumor compared to its expression level in transgenic cells." (PMID 21464922, 2011). "However, this tumor had integrations at both Tcf7l2 and Antxr1 which could potentially result in enhanced signaling by over-expression of 2 genes in the same WNT pathway." (PMID 22087314, 2011). "Two GRNs, albeit comprising a smaller number of tumor cells, showed high activity for the TCF7L2 regulon (along with KLF8, FOXK1, FOXP2, BACH1) (labeled TCF7L2+) and CTCF (along with MAFG and NR1H) (labeled CTCF+) respectively." (PMID 38645034, 2024). "Patients with nHM tumours with SMAD4 deletion had shorter RFS (HR = 2.13, 95% CI = 1.04–4.34), and those with TCF7L2 translocation had shorter OS (HR = 4.82, 95% CI = 2.10–11.03) and RFS (HR = 7.50, 95% CI = 2.72–20.69)." (PMID 39112715, 2024). "Next, HCCLM3 cells with stable TCF7L2 knockdown were injected into the liver of mice to construct orthotopic HCC implantation models, and the tumor metastasis in the liver of mice was observed 8 weeks later." (PMID 39060928, 2024). "Although the fetal tumor cluster displayed some regulon activity for TCF7 and TCF7L2, this was notably less pronounced compared to the embryonal tumor cluster." (PMID 39567475, 2024). "Two GRNs, albeit comprising a smaller number of tumor cells, showed high activity for the TCF7L2 regulon (along with KLF8, FOXK1, FOXP2, and BACH1) (labeled TCF7L2+) and CTCF (along with MAFG and NR1H) (labeled CTCF+), respectively." (PMID 38968122, 2024). "Among these factors, tumor stage, liver metastasis, surgical margin and SOX9&TCF7L2 staining (double‐high versus double‐low subgroup, HR = 2.23, 95% CI 1.10‐4.53, p = 0.026) remained significantly associated with OS in the multivariable analysis." (PMID 39492805, 2024). "Results of whole‐genome CRISPR screening from the DepMap project demonstrated strong tumor dependency of CDK7 in all tested GBC lines disregarding the expression levels of SOX9 and TCF7L2." (PMID 39492805, 2024). "Calcitriol reduces WNT-mediated tumor promotion, first, by VDR binding to β-catenin, impeding transcriptionally active TCF7L2/β-catenin complexes." (PMID 36364774, 2022). "Univariate analysis revealed that deeper tumor invasion (T stage), lymph node metastasis (N stage), advanced TNM stage, and high TCF7L2 expression were significantly correlated with a poor prognosis for patients with GC." (PMID 35864968, 2022). "Second, the survival analysis showed that 7 genes had significant (p < 0.05) Kaplan–Meier curves, including 5 genes (MS4A1, N4BP2L1, IGF1R, TCF7L2 and COL11A1) based on the normal expression, and 2 genes (TCF7L1 and PTPRM) based on the tumor expression." (PMID 35406404, 2022). "Taken together, these findings demonstrate that EphA2-SE plays an oncogenic role and promotes tumor progression in various tumors by recruiting FOSL2 and TCF7L2 to drive the expression of oncogene EphA2." (PMID 33712565, 2021). "The involvement of Wnt signaling pathway, including LEF1 and TCF7L2, in the promotion of invasion, CSC self-renewal, and metastasis of TNBC as well as other tumor types (i.e., lung and prostate) had been established." (PMID 29179446, 2017).
tumor (continued). "We found that knocking down TCF7L1 only modestly reduced tumor growth while knocking down both TCF7L1 and TCF7L2 significantly reduced the tumor size." (PMID 28467300, 2017). "Reassuringly, the resulting list includes several known colon tumor suppressors such as APC, TCF7L2, MCC, PTEN, and SMAD4." (PMID 29196508, 2017). "Based on these results, we suggest that the fusion transcripts produced between TCF7L2 and either VTI1A or RP11-57H14.3 are expressed at low levels in tumor samples, and some normal samples." (PMID 24608966, 2014). "With integrative analysis of whole genome CRISPR screening data from DepMap Project, GBC RNAseq data, and the Coltron prediction results, five CRC TFs (SOX9, TCF7L2, FOXA1, TGIF1 and HES1) were found to meet all our defined criteria for gene expression and tumor‐dependency levels." (PMID 39492805, 2024). "Notably, none of them has been well studied in BC, and our results demonstrated the biological functions and tumor expression of each gene in BC progression, which enriched the research profiles for the MITF/CCDC183-AS1/miR-4731-5p/TCF7L2 axis." (PMID 35957803, 2022). "Our meta-analysis of transcriptomics studies provides a clear picture of altered LEF/TCF gene expression, confirming TCF7L2 in normal and LEF1 expression in tumor tissue, but also higher than expected TCF7L1 in normal and relatively higher TCF7 expression in tumor tissue." (PMID 32403323, 2020). "We first tested our hypothesis about differential expression of LEF/TCF genes between tumor and normal tissue with forest plots of all four LEF/TCF genes (TCF7, LEF1, TCF7L1, TCF7L2)." (PMID 32403323, 2020). "Importantly, among the LEF/TCF genes, our meta-analysis also corroborates a switch from relatively higher TCF7L2 and TCF7L1 expression in normal control to relatively higher TCF7 and LEF1 expression in tumor tissue." (PMID 32403323, 2020). "MYC, miR-17-5p, and miR-20a are up-regulated by CCAT2 through transcription factor 7 like 2 (TCF7L2)-mediated transcriptional regulation and the interaction between CCAT2 and TCF7L2 results in an enhancement in WNT signaling activity, which promotes tumor growth and metastasis in CRC." (PMID 28108736, 2017). "However, the structural alterations, expression profiles, and functional roles of TCF7L2 in somatotroph tumours have not been fully elucidated." (PMID 38769659, 2024). "For example, MEF2A may play a dual role in promoting tumor proliferation and metastasis by inducing the activation of EMT and WNT/beta -catenin signaling, whereas TCF7L2 serves as a core TF of the WNT signaling pathway, and is involved in regulating tumor cell proliferation and migration." (PMID 39712016, 2024). "Notably, all sequenced DIAMOND tumours show a consistent upregulation of Ctnnb1 and Lef1, while Tcf7l2 is not differentially regulated." (PMID 37907668, 2023). "To examine whether the MIR100HG/hnRNPA2B1/TCF7L2 axis plays a role in cetuximab resistance of CRC patients, we obtained paired tumor specimens from 12 individuals before the start of cetuximab treatment and at the time of tumor progression." (PMID 35279145, 2022). "Furthermore, KAT2A and PPARD showed different expression levels based on the tumor stage, while TCF7L2 expression showed no significant change between different tumor grades." (PMID 36476410, 2022). "Other candidate markers with significantly altered mRNA levels from the qPCR array (SP1, E2F1, TCF7L2) exhibited comparable levels between tumor and adjacent normal tissues using immunohistochemistry without evident heterogeneity in terms of spatial distribution (data not shown)." (PMID 33063251, 2020). "TCF7L2 binds to and transactivate the enhancer of TCF7 gene with the coactivator β-catenin and promotes TCF7 transcription, while TCF7 down-regulates TCF7L2 target genes and acts as a feedback repressor of β-catenin/TCF7L2 with a potential function of tumor suppressor." (PMID 26289446, 2015).